CTLA4 (cytotoxic T-lymphocyte associated protein 4)
Diseases named in the same sentence as CTLA4 in open-access papers (continued):
Sharing a sentence is not in itself a finding about the gene and the disease.
tumor (continued). "Overexpression of programed death-ligand 1 (PD-L1) in tumor cells is correlated with poor prognosis, and immunotherapies with anti-PD-1/PD-L1 and anti-CTLA-4 antibodies have shown promising results in a variety of cancers." (PMID 28210259, 2017). "Anti-CTLA4 induces a proinflammatory environment characterized by increased immune infiltrates in the tumor and combines with radiation therapy to form protective immunity." (PMID 27893434, 2017). "The expression of CTLA-4, the immune checkpoint receptor, on Treg cells provides an important strategy for different tumor cells to evade host immune surveillance." (PMID 29179871, 2017). "Data from previous in vivo studies have shown that combinatorial blockade of CTLA-4 and PD-1 is an effective method for reducing tumor-specific immunosuppression." (PMID 28388539, 2017). "Here, the authors show that Newcastle Disease Virus (NDV) upregulates the inducible co-stimulator (ICOS) on T cells and that intratumoral targeting of ICOS with engineered NDV in combination with CTLA-4 blockade induces systemic anti-tumour immunity in mice." (PMID 28194010, 2017). "For further confirmation, we have co-cultured FOXP3-ablated CD8+ T cells in in vitro tumor milieu and checked the status of CTLA4-positivity." (PMID 28487507, 2017). "Amongst the non-CD8 T cells, significantly elevated frequencies of Tim-3+, PD-1+ and CTLA-4+ cells were again observed in tumour tissue." (PMID 28423034, 2017). "They increase T cell numbers and activity and thereby strengthen the anti-tumor response after treatment with anti-CTLA-4 or anti-PD-1 agents." (PMID 28361224, 2017). "and Burkholderiales, which control tumour progression by stimulating Th1 immune responses during anti-CTLA-4 therapy." (PMID 28404796, 2017). "Immune checkpoint antibodies that target the CTLA-4 and PD-1/PD-L1 inhibitory pathways are capable of reversing the inhibitory tumor-microenvironment and producing significant and long-lasting clinical responses." (PMID 28405494, 2017). "Here, we used FOXP3-transactivated cell surface protein, CTLA4, as a definitive phenotypic signature for tumor-CD8+ Treg cells." (PMID 28487507, 2017). "Fundamental advances in tumor immunology identified negative regulatory checkpoints (CTLA-4/PD-1) as key mediators of immune escape." (PMID 28923120, 2017). "Some other studies find blocking tumor-infiltrating macrophages with CSF1R inhibitor benefits the therapeutic effect of PD1 and CTLA4 antagonists, indicating tumor-associated macrophage (TAM) is a promising tumor therapy target." (PMID 29152078, 2017). "Subsequently, using the CT26 mouse tumor model we elucidated the effects of selumetinib alone or in combination with anti-CTLA-4 on various T-cell subsets and on the TME." (PMID 28807001, 2017). "We constructed tissue microarrays from tumor tissue samples and evaluated the immunohistochemical expression of CTLA-4 in 536 patients with primary resected stage I–IIIA NSCLC." (PMID 28707078, 2017). "CTLA-4 gene methylation was markedly correlated with GC when compared to the unmethylated gene (OR = 4.829; 95% CI: 2.46–9.48; p < 0.001) and the CTLA-4 expression profile was markedly higher in GC tissue samples than in normal tissue on the tumor margins." (PMID 28781967, 2017). "T cells expression of PD-1 and CTLA-4 showed impaired T cell function during the effector phase when engaged with their ligands and restrain anti-tumor immunity." (PMID 28750018, 2017). "By inhibiting CTLA-4, CTLs are (re-)activated and able to sufficiently help to reduce tumour burden." (PMID 29237435, 2017). "B16 tumors were implanted with both s.c. and directly into the brain, followed by i.t. injection of ISF35 in the s.c. tumor and i.p. administration of anti-PD-1 and anti-CTLA-4." (PMID 29129918, 2017). "Therapy with either the trAb BiLu or the anti-CTLA-4 mAb HB304 alone yielded identical survival benefits in comparison to the tumor control group." (PMID 27966460, 2017).
tumor (continued). "In animal models, this “in situ tumor vaccination”, while rarely effective as monotherapy, has shown synergy with various immunotherapy approaches including CTLA-4 blockade." (PMID 28239469, 2017). "Yet, studies examining the prognostic impact of CTLA-4 expression in NSCLC tumor tissue are few and inconclusive." (PMID 28707078, 2017). "Combined nivolumab (anti-PD-1) and ipilimumab (anti-CTLA-4) mediated inhibition results in enhanced T-cell function that is greater than the effects of either antibody alone, and results in improved anti-tumor responses in metastatic melanoma." (PMID 28219375, 2017). "PD-1 and CTLA-4 are critically involved in immune checkpoints, and potential tumor-reactive lymphocytes are often restrained by CTLA- and/or PD-1-transduced signals, reflecting the ability of many cancers to upregulate the corresponding ligands." (PMID 29156738, 2017). "Several phase I–II trials quickly revealed anti-tumor activities of the inhibitory anti-CTLA-4 antibody opening a novel strategy in cancer immunotherapy." (PMID 28497159, 2017). "Treatment with this combination of oncolytic NDV and anti-CTLA4 Ab led to systemic tumor rejection and subsequent protection of the host against tumor rechallenge in poorly immunogenic tumor models." (PMID 28555136, 2017). "In a phase I clinical trial of anti-CTLA-4 blockade in combination with anti-PD-1 inhibition, the combination of ipilimumab and nivolumab provided high tumor regression rates in patients with melanoma." (PMID 28361224, 2017). "As reported in previous studies, we found that CTLA-4 blockade or Cblb ablation led to a reduction of tumor growth and extended survival compared to wild-type IgG-treated mice." (PMID 28611299, 2017). "Mice were injected with vorinostat, a combination of anti-PD-1 and anti-CTLA-4 blockades, the three drugs in combination, or the vehicle as a control and tumor volume and percent change were measured." (PMID 29371976, 2017). "Local treatment of tumor-bearing mice with CTLA-4 functional antibody in a slow-release formulation is extremely effective in activating an endogenous tumor-specific CD8+ T cell response, capable of tumor eradication." (PMID 28099147, 2017). "Ipilimumab is a CTLA-4 inhibitor and nivolumab is a PD-1 inhibitor, both results in enhanced anti-tumor immune response." (PMID 28239468, 2017). "While the response to radiation was not affected by knockdown of cGAS in TSA cells, the improved control achieved in the presence of anti-CTLA4 with complete and durable tumour rejection was abrogated." (PMID 28598415, 2017). "Tumor tissue biomarkers were predominantly analyzed for correlations to response for both CTLA-4 and PD-1 ICI." (PMID 29034210, 2017). "In wild-type mice, CTLA-4 inhibition showed a marked efficacy in terms of decreased tumor growth and prolonged survival compared to IgG-treated control mice." (PMID 28611299, 2017). "In recent years, the use of anti-CTLA-4 antibodies has gained significant support and success in the treatment of several types of tumors; supposedly, by reinvigorating tumor-specific cytotoxic CD8+ T cells suppressed by CTLA-4-expressing Tregs." (PMID 28970798, 2017). "The presentation of tumor antigen by APCs to T-cells provides the initial signal for the immune system to target malignant cells, and CTLA-4 or PD-1/PD-L1 antibodies serve to disinhibit the response." (PMID 28730140, 2017). "We show here that T cells redirected to tumor cells by trAbs strongly upregulate CTLA-4 expression in vitro and in vivo." (PMID 27966460, 2017). "The combination of GM-CSF-secreting tumor cell vaccines and anti-CTLA-4 antibody was also demonstrated to increase the ratio of tumor-infiltrating CD8+ cytotoxic T cells to Tregs in preclinical and clinical studies." (PMID 29137370, 2017). "Tumor infiltrating gMDSC were modestly altered following CTLA-4 treatment compared to specific Ly6G depletion." (PMID 28915554, 2017).
tumor (continued). "Enhanced priming of tumor-specific T-cells is thought to be a principle mode of action for anti-CTLA-4." (PMID 28807001, 2017). "MC38/gp100 tumor-bearing mice were treated with solvent/antibody control (vehicle), ganetespib, anti-CTLA4 or anti-PD1, or the combination of ganetespib and anti-CTLA4 or anti-PD-1." (PMID 28878208, 2017). "GITR is constitutively expressed on Tregs similarly to CTLA-4 and the persistent expression of this molecule in the tumor environment was demonstrated." (PMID 28470464, 2017). "The combination of ganetespib and anti-CTLA4 conferred a better anti-tumor response, compared to either treatment alone and improved survival compared to either treatment alone." (PMID 28878208, 2017). "Here we sought to characterize the combined effects of MEK inhibition and anti-CTLA-4 mAb (anti-CTLA-4) therapy, examining effects on both T-cells and tumor microenvironment (TME)." (PMID 28807001, 2017). "Analysis of TILs from distant tumours revealed upregulation of CTLA-4 on the infiltrating Tcon and CD8+ cells in both NDV- and NDV-ICOSL-treated animals, although there was no major difference between the two viruses." (PMID 28194010, 2017). "As Cblb−/−mice are able to immunologically reject otherwise lethal tumor burdens, we wanted to investigate if this effect would be even more profound in combination with CTLA-4 or PD-L1 blockade." (PMID 28611299, 2017). "Tumor-infiltrating cells at baseline were investigated for response correlations in 20 CTLA-4 ICI studies and 15 PD-1 ICI studies." (PMID 29034210, 2017). "Another important check point molecule, CTLA4 is broadly engaged in tumor immune evasion through the down-regulation of CD4+ T effector (Teff) cells and the enhancement of Treg cell activity." (PMID 28878676, 2017). "This demonstrates heterogeneity of tumor cell CTLA-4 expression between PTs and LN+, probably brought about by genetic and epigenetic alterations acquired during tumor progression and metastasis." (PMID 28707078, 2017). "A turning point was the use of mAb that block PD-L1/PD-1 interaction, or anti-CTLA-4 mAb; all of them disrupting the tumor-induced suppression of antitumor immune responses." (PMID 29312320, 2017). "Best characterised for PD-1 and CTLA-4, these surface receptors on T cells are capable of delivering an inhibitory signal which reduces the anti-tumour function of these cells." (PMID 28423034, 2017). "Neutralizing PD-L1 with a monoclonal antibody also delayed tumor growth and extended survival, albeit to a lesser extent than CTLA-4 inhibition." (PMID 28611299, 2017). "This was, as the authors suggest, due to the cross-reactivity of the bacterial and tumour epitopes, which led to the restoration of the therapeutic response of GF tumour bearers to CTLA-4 antibody treatment." (PMID 29075294, 2017). "Pre-treatment with anti-CTLA4 antibodies before radiation therapy is optimal for tumor control in preclinical models and is consistent with successful clinical anecdotes and a retrospective review." (PMID 27893434, 2017). "Differently, IDO-KO mice have been shown to mount a good anti-tumor response following treatment with anti-CTLA-4 mAbs." (PMID 28404974, 2017). "In fact, it has been observed that the tumor samples obtained from cancer patients comprise increased number of immunosuppressive Tregs and cytokines as well as increased expression of CTLA-4 and PD-1 and their ligands." (PMID 28447025, 2017). "In our data, we observed that the expression of CTLA4 in the peritumoural area seems to have a high prognostic value, as it reflects the capacity of the host immune system to react against the tumour." (PMID 28988016, 2017). "Immune checkpoint blockade using monoclonal antibodies against PD-1, PDL-1 and CTLA-4 has been implemented as an immunotherapy strategy- resulting in restoration of T cell function and reduction of viral load or tumour growth." (PMID 29228684, 2017).
tumor (continued). "In the absence of anti-CTLA4 8GyX3 and 30 Gy were similarly effective at controlling the growth of the irradiated tumour, but complete durable regression of the irradiated tumour was achieved by addition of anti-CTLA4 only in mice treated with 8GyX3." (PMID 28598415, 2017). "There are two main negative regulators of T cell responses: checkpoints in lymphoid organs (CTLA-4) and immunostats within the tumour beds (PD-L1:PD-1)." (PMID 29075294, 2017). "Blockade of CTLA-4 and/or PD-1 has been shown to drastically diminish tumor growth and prolong survival in mice and patients in a T cell-dependent fashion." (PMID 28611299, 2017). "No discernable differences were observed in the frequency of tumor-infiltrating CTLA4+ CD8+ T cells from either wt or Cbx3/HP1γ-insufficient mice." (PMID 28220815, 2017). "Analysis of B16F10 tumours revealed reduced frequencies of CTLA-4+ Ki-67high Tregs after IL-2WTFc treatment, as well as a large increase in total leukocyte infiltration dominated by cytotoxic CD8+ T-cells." (PMID 28497796, 2017). "Clinical phase III studies with CTLA-4 ICM ipilimumab (Yervoy®) in metastatic melanoma have shown superiority in survival over tumour vaccination and a survival benefit in combination with chemotherapy versus chemotherapy alone." (PMID 29237435, 2017). "Combination therapy with NDV-ICOSL and anti-CTLA-4 led to regression of the majority of the virus-injected and distant tumours with long-term animal survival, which was superior to the combination of NDV-WT with anti-CTLA-4." (PMID 28194010, 2017). "The early preclinical studies have shown that the combination of PD-1/PD-L1 and CTLA-4 blockades is more than two times as effective as either alone to eradicate tumor cells." (PMID 27756892, 2017). "Apparently, these studies illustrate a dual role of CTLA-4 expression in tumor cells, and highlight the importance of further investigating mechanisms of upregulation, impact on prognosis and differences in CTLA-4 expression in tumor cells by cancer subtypes." (PMID 28707078, 2017). "Although repeated treatment with anti-CTLA-4 and anti-PD-1 as single-agent retarded tumor growth, tumor eradication was only observed when the HDACi was combined with the immunotherapy treatment." (PMID 29371976, 2017). "CTLA-4 blocking in tumour-bearing mice resulted in higher frequencies of mLama4- and mAlg8-specific T cells." (PMID 28916749, 2017). "Expression of CTLA-4 was analyzed in tumor and stromal primary tumor tissue and in locoregional metastatic lymph nodes." (PMID 28707078, 2017). "The expression of PD-1 and CTLA-4 on tumor infiltrating IC was successfully evaluated in 190 patients." (PMID 28460468, 2017). "Blocking antibodies for CTLA-4, PD-1 or PD-L1 seem to have a strong therapeutic potential when given alone or in combination with standard care of treatment in many different tumor entities." (PMID 28073373, 2017). "As a receptor expressed on CD4+, CD8+, and regulatory T-cells, CTLA-4 competitively disrupts the axis between tumour-specific T-lymphocytes bearing CD28 receptors and stimulatory ligands CD80 (B7) and CD86 (B70) on antigen-presenting cells." (PMID 28571578, 2017). "It was anticipated that the strong CD3-mediated T-cell activation induced by tumor-directed trAbs not only ignites T-cell effector functions, but also entails CTLA-4 upregulation on the surface of activated T cells." (PMID 27966460, 2017). "In this model, NKTR-214 proved efficacy as a single agent, and long-term immunity when combined with antagonist CTLA-4 mAb, in addition to resistance to tumor rechallenge." (PMID 28970830, 2017). "Immune checkpoint receptors such as PD-1 and CTLA-4 not only play important roles in immune homeostasis, but these inhibitory pathways are also utilized by tumor cells for immune response evasion." (PMID 28603527, 2017). "Potential heterogeneity in CTLA-4 expression within the tumor tissue was minimized by analyzing cores from two to four areas of tumor and of stroma." (PMID 28707078, 2017).
tumor (continued). "Another study observed that only fractionated RT induced an AE in a secondary tumor when combined with anticytotoxic T-lymphocyte antigen-4 (CTLA-4) antibody immunotherapy." (PMID 28222111, 2017). "Our in vivo studies further show the relative ineffectiveness of PD-1 blockade alone and the necessity to co-inhibit both the PD-1 and CTLA-4 pathway to have a significant anti-tumor effect." (PMID 29371976, 2017). "Antibody blockade of CD96 in mouse models promoted NK cell function and anti-tumor response, both alone and in combination with anti-CTLA-4 or anti-PD-1 treatment." (PMID 29211042, 2017). "Pursuing the idea in animal models, his group showed that the antibody mediated blockade of CTLA-4 indeed leads to tumor regression." (PMID 28497159, 2017). "For example, a phase II trial in metastatic melanoma patients has shown that compared with ipilimumab (CTLA-4 blockade) monotherapy, the combination of ipilimumab and GM-CSF resulted in enhanced overall survival rate and tumor reduction with less toxicity." (PMID 28567163, 2017). "AR42 and sodium valproate both significantly enhanced the anti-tumor efficacy of an anti-PD-1 antibody and of an anti-CTLA4 antibody." (PMID 29137331, 2017). "CTLA-4 and PD-1 regulate different inhibitory pathways, and combination therapies with antibodies targeting both molecules have been shown to improve anti-tumor response in a mouse model." (PMID 28361224, 2017). "The inhibition of this receptor-ligand interaction using an anti-CTLA-4 antibody results in the reactivation and proliferation of T cells and also decreases the immunosuppressive Treg cells in the tumor microenvironment." (PMID 28434400, 2017). "And preclinical studies already proved that CTLA-4 inhibition achieved prolonged overall survival and stabilization on GL-261 tumor-bearing mice and immunocompetent VM/Dk mice, along with considerable safety and toleration." (PMID 28536525, 2017). "Binding of CTLA4 with its ligand on APCs triggered apoptosis of tumor cells further inhibited tumor progression." (PMID 28174608, 2017). "Amongst CD8 T cells, the frequency of Tim-3, CTLA-4 and PD-1 expressing cells was significantly greater in the tumour relative to the blood, a pattern that was repeated for Tim-3, CTLA-4 and PD-1 amongst non-CD8 T cells." (PMID 28423034, 2017). "We did not detect the appearance of novel T-cell specificities against any of the epitope candidates tested here, thus suggesting a CTLA-4-dependent tumour-specific effect on the two dominant antigen-specific T cells in this model." (PMID 28916749, 2017). "We detected a significant increase in the magnitude of mLama4- (~2-fold) and mAlg8- (~1.5-fold) specific T-cell responses in tumours from mice that received anti-CTLA-4 mAbs." (PMID 28916749, 2017). "It has been demonstrated that the blockade of CTLA-4 augments endogenous responses to tumor cells, thus leading to tumor cell death in breast cancer." (PMID 28680165, 2017). "Antibody blockade of PD-1 and CTLA-4 restores anti-tumour immunity and leads to durable clinical responses in a subset of patients." (PMID 28423034, 2017). "The combination of T-DM1 and anti-CTLA4 or anti-PD-1 antibodies, elicited responses in tumour xenografts that had previously been resistant to T-DM1 monotherapy in a mouse model." (PMID 28916815, 2017). "Baseline tumor-specific CD8+ T-cell responses showed correlations to both CTLA-4 ICI and PD-1 ICI response, but potential correlations to PFS or OS were not analyzed." (PMID 29034210, 2017). "Rejection of the irradiated and abscopal TSA tumours in mice treated with 8GyX3+anti-CTLA4 was abrogated in Batf3−/− and interferon-α/β-receptor-1 (IFNAR1)−/− mice, demonstrating the requirement for CD8α+ TIDCs responsive to IFNβ." (PMID 28598415, 2017).